LIPM (lipase family member M)
Description:
Plays a highly specific role in the last step of keratinocyte differentiation. May have an essential function in lipid metabolism of the most differentiated epidermal layers.
Synonyms: LIPL3; bA304I5.1
Tractability: Small molecule: it belongs to a druggable protein family. Antibody: UniProt places it where antibodies can reach, with high confidence; its Gene Ontology location is reachable by antibodies, with high confidence; UniProt predicts a signal peptide or a membrane-spanning region.
Gene: Protein-coding gene on chromosome 10 (88,802,730 to 88,820,546, forward strand). Ensembl gene ENSG00000173239.
Subcellular location: Secreted
Subcellular location (Human Protein Atlas): Endoplasmic reticulum; Predicted to be secreted
Pathways (Reactome):
Developmental Biology: Formation of the cornified envelope
Gene Ontology:
Molecular function: lipoprotein lipase activity; carboxylic ester hydrolase activity; hydrolase activity, acting on ester bonds; lipase activity
Biological process: cornification; lipid metabolic process
Cellular component: extracellular region
Genetic constraint (gnomAD): Loss-of-function variants: 28 observed, 31.01 expected, observed/expected ratio (o/e) 0.9, 90% interval 0.67 to 1.24. The upper end of that interval is the gene's LOEUF score, 1.24, which puts it in group 5 of 6, group 1 being the genes least tolerant of losing a copy. Missense variants: 466 observed, 481.62 expected, observed/expected ratio (o/e) 0.97, 90% interval 0.9 to 1.04. Synonymous variants: 158 observed, 163.01 expected, observed/expected ratio (o/e) 0.97, 90% interval 0.85 to 1.11.
Homologues: Orthologues: chimpanzee LIPM (99% identical), macaque LIPM (98% identical), pig LIPM (90% identical), rabbit LIPM (89% identical), rat Lipm (88% identical), mouse Lipm (87% identical), dog LIPM (87% identical), guinea pig LIPM (86% identical), Caenorhabditis elegans lipl-2 (38% identical), Caenorhabditis elegans lipl-5 (37% identical), Caenorhabditis elegans lipl-1 (36% identical), Caenorhabditis elegans lipl-6 (35% identical), and 24 more. Paralogues in human: LIPA (57% identical), LIPK (50% identical), LIPF (49% identical), LIPN (48% identical), LIPJ (46% identical).
Diseases named in the same sentence as LIPM in open-access papers:
LIPM is named in the same sentence as 3 diseases in open-access papers, as found by Europe PMC text mining. Sharing a sentence is not in itself a finding about the gene and the disease. The quoted sentences say what the papers report.
infection (3 papers, 2016 to 2025). The state of being infected such as from the introduction of a foreign agent such as serum, vaccine, antigenic substance or organism. "We have thus far determined that LipA, LipM, and LipL comprise components of the de novo lipoic acid biosynthesis pathway and LplA1 and LplA2 constitute enzymes involved in lipoic acid salvage with LplA2 exerting its most notable activity during infection." (PMID 27701474, 2016).
cancer (2 papers, 2021 to 2023). A tumor composed of atypical neoplastic, often pleomorphic cells that invade other tissues. "The overexpression and copy number amplification of ANKRD22 and LIPM in early cancer, and overexpression, mutation, and copy number amplification of IGHA1 in early cancer may all promote early metastasis." (PMID 37152984, 2023).
LIPM also shares sentences with these, for which no sentence is quoted: tauopathy (1 paper).